ZNF521 (zinc finger protein 521)
Description:
Transcription factor that can both act as an activator or a repressor depending on the context. Involved in BMP signaling and in the regulation of the immature compartment of the hematopoietic system. Associates with SMADs in response to BMP2 leading to activate transcription of BMP target genes. Acts as a transcriptional repressor via its interaction with EBF1, a transcription factor involved specification of B-cell lineage; this interaction preventing EBF1 to bind DNA and activate target genes.
Synonyms: EHZF; Evi3
Tractability: PROTAC: UniProt records ubiquitination sites on it.
Gene: Protein-coding gene on chromosome 18 (25,061,924 to 25,352,194, reverse strand). Ensembl gene ENSG00000198795.
Subcellular location: Nucleus
Subcellular location (Human Protein Atlas): Nucleoplasm
Pathways (Reactome):
Developmental Biology: Formation of the anterior neural plate; Formation of the posterior neural plate
Gene expression (Transcription): RUNX2 regulates osteoblast differentiation
Gene Ontology:
Molecular function: protein binding; protein domain specific binding; transcription cis-regulatory region binding
Biological process: regulation of transcription by RNA polymerase II
Cellular component: nucleoplasm; nucleus
Genetic constraint (gnomAD): Loss-of-function variants: 13 observed, 100.25 expected, observed/expected ratio (o/e) 0.13, 90% interval 0.083 to 0.21. The upper end of that interval is the gene's LOEUF score, 0.21, which puts it in group 1 of 6, group 1 being the genes least tolerant of losing a copy. Missense variants: 1,207 observed, 1,664.4 expected, observed/expected ratio (o/e) 0.73, 90% interval 0.69 to 0.76. Synonymous variants: 628 observed, 628.77 expected, observed/expected ratio (o/e) 1, 90% interval 0.94 to 1.07.
Homologues: Orthologues: chimpanzee ZNF521 (99% identical), macaque ZNF521 (99% identical), dog ZNF521 (99% identical), guinea pig ZNF521 (98% identical), pig ZNF521 (98% identical), rabbit ZNF521 (98% identical), mouse Zfp521 (97% identical), rat Zfp521 (97% identical), tropical clawed frog znf521 (91% identical), zebrafish ZNF521 (65% identical), zebrafish znf521 (29% identical), Caenorhabditis elegans ztf-16 (7% identical), and 3 more. Paralogues in human: ZNF423 (63% identical), ZNF462 (22% identical), ZNF445 (12% identical), ZNF786 (10% identical), ZNF211 (8% identical), ZBTB39 (8% identical), ZNF597 (6% identical).
Diseases named in the same sentence as ZNF521 in open-access papers:
ZNF521 is named in the same sentence as 48 diseases in open-access papers, as found by Europe PMC text mining. Sharing a sentence is not in itself a finding about the gene and the disease. The quoted sentences say what the papers report.
medulloblastoma (8 papers, 2013 to 2022). A malignant, invasive embryonal neoplasm arising from the cerebellum. "Among its diverse activities, ZNF521 has been implicated in the regulation of medulloblastoma (MB) cells, where the Hedgehog (HH) pathway, has a key role in the development of normal cerebellum and of a substantial fraction of MBs." (PMID 31558698, 2019). "In conclusion, the data illustrated in this paper implicate the stem and progenitor cell factor ZNF521 and its association with the NuRD complex in the control of the growth of at least a subset of medulloblastomas." (PMID 23907569, 2013). "Consistently, ZNF521 has been shown to stimulate the growth, clonogenicity, and tumorigenicity of human and murine medulloblastoma stem-like cells." (PMID 26788497, 2015). "ZNF521 is highly expressed in cerebellum and in particular in the neonatal external granule layer that contains candidate medulloblastoma cells-of-origin, and in the majority of human medulloblastomas." (PMID 23907569, 2013). "Conversely, silencing of ZNF521 in human UW228 medulloblastoma cells that display high baseline expression decreased their proliferation, clonogenicity, sphere formation and wound-healing ability." (PMID 23907569, 2013). "Our data strongly support the notion that ZNF521, through the recruitment of the NuRD complex, contributes to the clonogenic growth, migration and tumorigenicity of medulloblastoma cells." (PMID 23907569, 2013). "The role of ZNF521 in hematopoetic tissues and its effects on the clonogenic and in vivo growth of human and murine medulloblastoma cells suggests a potential requirement in stem-like tumor cells." (PMID 23907569, 2013). "The results show that, with the exception of Group 3 MBs, ZNF521 expression in medulloblastomas is comparable to that of adult cerebellum, with a considerable fraction of the tumors in the SHH subgroup and Group 4 MBs displaying high expression levels." (PMID 23907569, 2013). "The results of this study highlight a strong relationship between activity of this factor and growth and tumorigenic potential of human and mouse medulloblastoma cells, indicating that ZNF521 is likely to play a role in the pathogenesis of this tumor." (PMID 23907569, 2013). "We examined the ZNF521 mRNA expression levels in a series of previously published analyses as well as unpublished data, comprising a total of 436 cases of medulloblastomas and 18 normal cerebellum specimens." (PMID 23907569, 2013). "To gain further evidence of the involvement of ZNF521 in the pathogenesis of medulloblastoma, we exploited the availability of one of these models and investigated the role of Zfp521 in primary mouse MB cells." (PMID 23907569, 2013). "Given the high expression of ZNF521/Zfp521 in the cerebellum - and especially in the external granule layer during its development - we decided to investigate the role of ZNF521 in medulloblastoma." (PMID 23907569, 2013). "Moreover, ZNF521 contributes to the clonogenic growth, migration and tumorigenicity of medulloblastoma cells." (PMID 32913476, 2020). "ZNF521 transcript is abundant in the brain, particularly in neural stem cells and cerebellar granule neuron precursors, which are considered the cells of origin of a substantial fraction of medulloblastomas, the most common malignant brain tumours in children." (PMID 26788497, 2015). "The pro-clonogenic effects of ZNF521 in soft agar and in serum-free liquid cultures suggest that this factor may play a role in a stem-like population of cells in human medulloblastoma cell lines." (PMID 23907569, 2013). "Enforced overexpression of ZNF521 in DAOY medulloblastoma cells significantly increased their proliferation, growth as spheroids and ability to generate clones in single-cell cultures and semisolid media, and enhanced their migratory ability in wound-healing assays." (PMID 23907569, 2013).
medulloblastoma (continued). "In the light of this concept, the growth rate profiles obtained from the sphere assays suggest that ZNF521 may enhance the self-renewal in a subset of primitive DAOY cells that could be related to medulloblastoma-initiating cells." (PMID 23907569, 2013). "ZNF521 enhances clonogenicity of DAOY medulloblastoma cells." (PMID 23907569, 2013). "In addition to the hematopoietic system, ZNF521 has recently been demonstrated to drive the generation of neuroectodermal precursors from embryonic stem cells and to contribute to the growth, clonogenicity, and tumorigenicity of medulloblastoma cells." (PMID 24976683, 2014). "This notion was supported by the increase of in vivo tumorigenicity we observed in DAOY cells expressing full-length ZNF521, as well as the decrease in development and growth rate of tumor xenografts following silencing of the abundantly-expressed Zfp521 gene in cells from Ptc1−/+ medulloblastomas." (PMID 23907569, 2013). "In the light of its abundance in immature neural cells (including cerebellar granule neurons precursors) and in the majority of human medulloblastomas, and of its recognized role as one of the earliest inducers of neural development, ZNF521 could be a factor involved in this process." (PMID 23907569, 2013). "The expression of ZNF521 in primary OA chondrocytes was considerably high and comparable to that observed in the hematopoietic cell lines THP1, K562 and in the medulloblastoma cell line DAOY, which have been shown to depend on a functionally active ZNF521." (PMID 24976683, 2014). "However, better differentiated cells may also require its activity, and additional studies will be required to determine the precise contribution of ZNF521 to medulloblastoma pathogenesis and its potential utility as a candidate target for advanced therapeutic approaches in MB-initiating cells." (PMID 23907569, 2013). "To investigate the role of ZNF521 in the regulation of human MB cells we used the DAOY cell line, which was derived from a biopsy of desmoplastic medulloblastoma." (PMID 23907569, 2013). "Western blotting analysis of 5 medulloblastoma specimens in comparison with non-neoplastic cerebellar tissue confirmed the presence of equivalent amounts of ZNF521 protein." (PMID 23907569, 2013). "To address this possibility we investigated the effects of ZNF521 in DAOY, a cell line commonly employed as a model for human medulloblastoma whose moderate expression of ZNF521 makes it amenable to the study of the biological effects of both overexpression and knock-down of this factor." (PMID 23907569, 2013).
gastric cancer (7 papers, 2020 to 2024). A primary or metastatic malignant neoplasm involving the stomach. "ZNF521 expression has also been associated with the prognosis of pediatric neuroblastoma, gastric cancer, CRC, and ovarian cancer." (PMID 39025327, 2024). "Within this family, AKR1B1 has been implicated in gastric cancer progression, regulated by the binding of ZNF521 and EB1, promoting proliferation, migration, and invasion of gastric cancer cells." (PMID 38440405, 2024). "Through database analysis, we showed that high ZNF521 expression was significantly associated with poor survival outcomes in ovarian cancer, gastric cancer, colon adenocarcinoma, bladder cancer, lung squamous cell carcinoma, and thyroid cancer." (PMID 36311294, 2022). "Interestingly, we found that ZNF521 expression was associated with higher immune infiltration in gastric cancer and poor prognosis." (PMID 36311294, 2022). "The results showed that ZNF521 expression was significantly related to most of the markers for various immune cells and T cells in gastric cancer." (PMID 36311294, 2022). "ZNF521 expression levels in gastric cancer tissues were 58.7% (256/436), which was higher than in normal tissues (20.6% [19/92])." (PMID 36311294, 2022). "ZNF521 is correlated significantly with immune cell infiltration and is a valuable biomarker for prognosis in gastric cancer." (PMID 36311294, 2022). "In particular, we analyzed the prognostic value of ZNF521 expression in gastric cancer patients with lymphatic metastasis." (PMID 36311294, 2022). "In stage III gastric cancer, 5-year survival was significantly lower in patients with high ZNF521 expression compared with patients with low expression (P < 0.05)." (PMID 36311294, 2022). "ZNF521 promotes the malignant characteristics of gastric cancer cells in part by interacting with immune infiltrating cells." (PMID 36311294, 2022). "The results of analysis of these databases showed that increased ZNF521 expression had a poor prognostic value in gastric cancer." (PMID 36311294, 2022). "We used the Kaplan–Meier Plotter database to investigate the relationship between ZNF521 expression and the clinical characteristics of gastric cancer patients." (PMID 36311294, 2022). "The prognostic value of ZNF521 on the basis of Affymetrix microarray data in gastric cancer was evaluated using the Kaplan–Meier Plotter database." (PMID 36311294, 2022). "In this study, we detected ZNF521 expression in gastric cancer by immunohistochemistry (IHC) and analyzed the correlation between its expression with pathological parameters and prognosis." (PMID 36311294, 2022). "Kaplan–Meier plotter databases were used to analyze the expression of ZNF521 and its correlation with the prognosis of gastric cancer." (PMID 36311294, 2022). "ZNF521 can also arrest apoptosis and enhance the proliferation, migration, and invasion of gastric cancer cells via regulating microRNA-204-5p." (PMID 36311294, 2022). "The Kaplan–Meier method was used to analyze the effects of ZNF521 on the prognosis of gastric cancer patients." (PMID 36311294, 2022). "Immunohistochemistry analysis demonstrated that the ZNF521 protein was highly expressed in gastric cancer tissues (GC) compared to adjacent normal tissues." (PMID 34445164, 2021). "ZNF521 ectopic expression enhanced the proliferation, migration, and invasion of gastric cancer cell lines." (PMID 34445164, 2021). "The expression of ZNF521 was up-regulated in gastric cancer samples." (PMID 36311294, 2022). "Expression of ZNF521 was examined by immunohistochemistry in gastric cancer cases." (PMID 36311294, 2022). "Additionally, the correlation between ZNF521 expression and immune cell markers indicates that ZNF521 regulates tumor immunity in bladder cancer, lung squamous cell carcinoma, and gastric cancer." (PMID 36311294, 2022). "Thus, ZNF521 expression may affect the prognosis of gastric cancer patients by promoting lymph node metastasis." (PMID 36311294, 2022).
gastric cancer (continued). "In gastric cancer cells, low expression of miRNA-204-5p facilitates the proliferation, migration, and invasion of GC cells permitting an upregulating ZNF521." (PMID 34445164, 2021). "The expression of ZNF521 was correlated with infiltrating levels of CD4+ T and CD8+ T cells, macrophages, neutrophils, and dendritic cells in gastric cancer, which also correlated with diverse immune marker sets." (PMID 36311294, 2022). "We further analyzed the correlation between ZNF521 expression and markers of monocytes, TAMs, and M1 and M2 macrophages in the GEPIA database of gastric cancer." (PMID 36311294, 2022). "Understanding the molecular relationship between ZNF521 expression in GC cells could open new horizons for the identification of clinical-pathological features and molecular prognostic markers for gastric cancer patients." (PMID 34445164, 2021). "Among this group of genes, aberrantly methylated in other human cancers were CCR6 in oral cancer and chronic lymphocytic leukemia, RAB37 in lung cancer, ZNF521 in breast cancer, and CDX1 in gastric cancer, esophageal SCC, and in colon cancer." (PMID 32961999, 2020). "ZNF521 expression was correlated with levels of infiltrating CD4+ and CD8+ T cells, macrophages, neutrophils, and DCs in bladder cancer, lung squamous cell carcinoma, and gastric cancer, and was also correlated with diverse immune markers." (PMID 36311294, 2022). "According to the IHC scores, ZNF521 expression was higher in gastric cancer tissues than in non-tumor gastric tissues." (PMID 36311294, 2022).
leukemia (6 papers, 2015 to 2022). A malignant (clonal) hematologic disorder, involving hematopoietic stem cells and characterized by the presence of primitive or atypical myeloid or lymphoid cells in the bone marrow and the blood. "Knockdown of ZNF521 with short-hairpin RNA (shRNA) led to decreased leukemia proliferation, reduced colony formation and caused cell cycle arrest in MLL-rearranged AML cell lines." (PMID 28412727, 2017). "The mouse zinc‐finger gene Zfp521 (also known as ecotropic viral insertion site 3; Evi3; and ZNF521 in humans) has been identified as a B‐cell proto‐oncogene, causing leukemia in mice following retroviral insertions in its promoter region that drive Zfp521 over‐expression." (PMID 27506447, 2016). "In this paper, we used data mining and gene expression analysis to dissect the profile of ZNF521 mRNA in different leukemias." (PMID 34639154, 2021). "Supporting the idea that ZNF521 is particularly required for MLL-mediated leukemia, our data of luciferase reporter and ChIP assays revealed that ZNF521 is a direct target of both MLL-AF9 and MLL-ENL fusion proteins." (PMID 28412727, 2017). "In conclusion, our findings identify ZNF521 as a critical effector of MLL fusion proteins in blocking myeloid differentiation and highlight ZNF521 as a potential therapeutic target for this subtype of leukemia." (PMID 28412727, 2017). "Recently, independent gene expression profile studies have evidenced a positive correlation between ZNF521 mRNA overexpression and MLL-rearranged acute myeloid leukemia (AML), leaving open the question on the role of ZNF521 in this subtype of leukemia." (PMID 28412727, 2017). "Links between ZNF521 (the human orthologue of Zfp521) and human leukemia also exist, as a translocation that generates a chimaeric fusion protein of ZNF521 and PAX5 has been found in paediatric acute lymphoblastic leukemia." (PMID 27506447, 2016). "By performing gene expression profiling in HSCs in which the expression of both MLL-AF9 and ZNF521 was modulated by lentiviruses, we extended the panel of the genes and pathways potentially involved in this leukemia, which will help to design better targeted therapies." (PMID 34639154, 2021). "Interestingly, the expression of either HOXA9, a canonical downstream target for MLL-rearranged leukemia or ZNF521 have been shown to be restricted in CD34+ progenitor cells." (PMID 28412727, 2017). "Furthermore, our results support the direct activation of ZNF521 by MLL fusion proteins increasing the importance of this transcription factor in the transformation of the leukemia cells." (PMID 28412727, 2017). "On this way, our data show that the most relevant effect of ZNF521 depletion was to enhance myeloid differentiation of leukemia cells as evidenced by changes in cell morphology, immunophenotype and increase of a myeloid-specific gene expression in MLL-rearranged cell lines and primary cells." (PMID 28412727, 2017). "It has thus been proposed that up‐regulation of ZNF521 in rare leukemia initiating cells may facilitate tumor progression, even though ZNF521 over‐expression is not detected in the majority of leukaemic B‐cells from patients." (PMID 27506447, 2016). "Whether the presence of ZNF521 in ALL leukaemia-initiating cells is limited to those expressing MLL-AF9 or is a more general feature remains to be established." (PMID 26788497, 2015). "Thus, the events documented after ZNF521 depletion, which in part resemble what has been previously observed in MLL-rearranged cells after loss of HOXA9, gave a further support that ZNF521 plays a critical role in MLL-fusion-mediated leukemia." (PMID 28412727, 2017). "ZNF521 is a critical effector of KMT2A fusion proteins in blocking myeloid differentiation and can be used as a potential therapeutic target for this leukemia subtype." (PMID 36139405, 2022).
leukemia (continued). "Other transcriptional regulatory factors that are induced by both ZNF521 and MA9 at the early stages of leukemia development have various roles in controlling transcriptional activation, and some have been more recently associated with leukemias." (PMID 34639154, 2021). "Thus, MLL fusion proteins might promote leukemogenesis not only by HOXA9 and MEIS1 upregulation, but also by keeping the ZNF521 overexpressed, which in turn contributes to a block of differentiation or to the maintenance of an undifferentiated state of leukemia cells." (PMID 28412727, 2017). "Additionally, we also used the THP-1 human leukemia cell line carrying an MLL-AF9 rearrangement and expressing high amounts of ZNF521." (PMID 34639154, 2021). "Concerning the role of ZNF521, several gene expression profiling data sets have revealed high expression, especially in leukemic patients with MLL rearrangements compared to other leukemias." (PMID 34639154, 2021). "How can the apparent lack of ZNF521 expression in ALLs be reconciled with its proposed role as a driver in these leukaemias?" (PMID 26788497, 2015).